CD4 (CD4 molecule)
Diseases named in the same sentence as CD4 in open-access papers (continued):
Sharing a sentence is not in itself a finding about the gene and the disease.
Autoimmunity (continued). "We have identified that the changes of the luminal microenvironment of the intestine resulting from Ahr knockout in CD4+ cells lead to decreased post-activation lifespan in T cells; however, the impact of these changes on other cell types and other models of autoimmunity have yet to be determined." (PMID 36787309, 2023). "More specifically, CD4 T cell phenotype plays a central role in autoimmune disorders." (PMID 36901757, 2023). "Accordingly, we hypothesized that Treg may also have the capacity to suppress the activation of autoreactive CD4+ T cells that are considered to drive autoimmunity." (PMID 38022661, 2023). "Overall, these results indicated that RNF157 may serve a critical role in autoimmunity through regulating the differentiation of CD4+ T cell subpopulations." (PMID 37441600, 2023). "Although a clearly defined set of surface markers remains to delineate cytotoxic CD4+ T cells from other CD4+ T cell subsets, there is a growing interest in the role of this cytotoxic subset in fighting infectious diseases, promoting autoimmunity, and eliminating cancers." (PMID 37892982, 2023). "The development of autoimmunity to the neutrophil protein myeloperoxidase (MPO) involves loss of tolerance to this self-antigen with activation of the innate immune system, production of MPO-ANCAs and the proliferation of effector anti-MPO CD4+ T cells." (PMID 36674855, 2023). "It is altered in autoimmune disorders and has been hypothesized to be important in the successful adaptation of maternal immunity during pregnancy, indicating that the CD4/CD8 ratio in blood could be a promising immunophenotypic marker for human reproduction." (PMID 36968684, 2023). "In addition to their role in preventing autoimmunity, CD4+CD25+ T cells that express FOXP3 have been shown to be important for suppressing alloimmunity and for inducing and maintaining allograft tolerance." (PMID 37874660, 2023). "Also, TRAIL+ NK cells have been proposed to eliminate CD4+ T cells in a model of CMV‐induced autoimmunity." (PMID 37916875, 2023). "Another reason is that protocols for differentiating some lymphocytes associated with autoimmunity, such as CD4+T cells or B cells, from iPS cells have not been well established." (PMID 37876023, 2023). "Additionally, CD4 + T helper cells are major players in humoral immunity, pathogen protection, and autoimmunity induction." (PMID 37735184, 2023). "Considering that CD4+ T cells are indispensable to protecting the organism against fungal infections, an overactivation of these immune cells could potentially lead to autoimmunity." (PMID 37374092, 2023). "In autoimmunity, CD4+ CD28- cells are expanded, but these were normally represented in our patient." (PMID 37371700, 2023). "The third category is an anti-inflammatory CD4+ population called regulatory T-cells (Tregs), which suppress inflammatory responses, promote immunological tolerance, and control immune responses to prevent autoimmunity." (PMID 36769019, 2023). "In this context, it's worth noting that research has shown that intestinal CD4+ T cells may develop CNS autoimmunity and that T-cell activation occurs in the gut." (PMID 38090441, 2023). "CD4+ Foxp3+ Tregs played an important role in preventing autoimmunity in mice and humans." (PMID 36189304, 2022). "Th 17 cells and Treg cells, which were differentiated from CD4+ T cells, promote tissue inflammation and suppress autoimmunity respectively, understanding and regulating the balance between Th17/Treg cells would contribute to the treatment and prevention of IgAN and IBD." (PMID 35769467, 2022). "It is notable that CD4+ T-cells are of fundamental importance in mediating autoimmunity." (PMID 36505471, 2022). "Further investigation is warranted to understand the complexities of CD8+ Tfh-like and CD4+ Tfh mediated responses and how these similar cell populations may synergistically contribute to autoimmunity." (PMID 35493515, 2022).
Autoimmunity (continued). "ETS1 is a transcription factor highly expressed in CD4 T-cells known to regulate differentiation, survival and proliferation of lymphoid cells; the ETS1 locus is an important genetic regulator of risk for the autoimmune disorder systemic lupus erythematosus." (PMID 35100265, 2022). "Environmental protection should be taken seriously because the excess of these toxicants may help in promoting autoimmunity through alterations in DNA methylation in CD4 T cells." (PMID 35967306, 2022). "CD4+FOXP3+ Treg are known for their essential role in preventing autoimmunity." (PMID 36346673, 2022). "CD4+FoxP3+ regulatory T cells (Treg) are crucial for the regulation of T cell responses in the peripheral lymphatic organs and thus for the prevention and control of autoimmunity." (PMID 36389689, 2022). "Additionally, an excess of these toxicants helps in promoting autoimmunity through alterations in DNA methylation in CD4 T cells." (PMID 35967306, 2022). "Th17 cells are the other lineage of effector CD4+ T cells that drive autoimmunity." (PMID 36233291, 2022). "As several studies suggested that circulating Tfh cells were associated with autoimmunity, we first compared the frequency of CD4+CD45RA–CXCR5+ cells in total CD4+ T cells in patients with SLE (14 with a SLEDAI ≤ 4 and 13 with a SLEDAI > 4) with that in healthy controls (20 age- and sex-matched)." (PMID 35865165, 2022). "They described CD4+CD25+ T cell that controlled autoimmunity as activated T cells." (PMID 36426347, 2022). "We were particularly interested in whether T-helper 17 cells (Th17) — a subset of CD4+ cells — had an increased response, since this T cell subtype exhibits higher expression of the IL-7 receptor, IL-7R α and has a key role in autoimmunity." (PMID 35015072, 2022). "Moreover, CD4+ T cells that fail to express Blimp1 (Prdm1-/-) preferentially differentiate into Tfh, at an accelerated rate, in vivo, generally resulting in autoimmunity." (PMID 35493515, 2022). "Finally, we demonstrate that these self-reactive interactions between CD4+ thymocytes and mTECs critically prevent multiorgan autoimmunity." (PMID 35188458, 2022). "The circulating CD4+CXCR5+FOXP3+ Tfrs with enhanced suppressive function could alleviate autoimmunity in RA patients by reducing IgG and IgM levels, and the proportion of Tfrs was negatively correlated with the disease severity." (PMID 35474948, 2022). "Moreover, tumor necrosis factor (TNF)-related apoptosis-inducing ligand (TRAIL)-expressing SG NK cells control CD4+ T cell response during chronic viral infection to limit autoimmunity." (PMID 36388880, 2022). "Finally, we demonstrate that disrupted MHCII/TCR interactions between mTECs and CD4+ thymocytes lead to the generation of mature T cells containing self-specificities capable of inducing multiorgan autoimmunity." (PMID 35188458, 2022). "CD4+ T cells can differentiate into anti-inflammatory subtypes, such as Type 2 helper (Th2) cells, and pro-inflammatory subtypes, such as Type 1 helper (Th1) cells and Type 17 helper (Th17) cells; T regulatory cells (Tregs) are one necessary CD4+ T subtypes in preventing autoimmunity." (PMID 36056051, 2022). "CD4+ conventional T cells (Tconvs) mediate adaptive immune responses, whereas regulatory T cells (Tregs) suppress those responses to safeguard the body from autoimmunity and inflammatory diseases." (PMID 35844585, 2022). "NLRC3 is expressed both in CD4+ T cells and in DCs and limits autoimmunity by different pathways." (PMID 35619184, 2022). "Previous studies revealed that α‐syn could induce autoimmunity of CD4+‐ and CD8+‐T cells to delay the process of PD." (PMID 35789066, 2022). "Regarding CCR4, increased expression in AN on CD4+ T cells, which may represent Th17 cells, could promote autoimmunity and chronic inflammation." (PMID 36226111, 2022). "ALKBH5 controls the pathological effects of CD4+ T cells during autoimmunity." (PMID 35682869, 2022).
Autoimmunity (continued). "CXCR5+CD4 T follicular helpers (CD4 Tfh) have received most of the limelight for their contribution to germinal center migration, functionality, and B cell help within infection, cancer, and autoimmunity." (PMID 36314014, 2022). "Pro-inflammatory CD4+ T helper (Th) cells drive the pathogenesis of many autoimmune conditions." (PMID 35250997, 2022). "• Constitutive Akt1 signaling contributes to proliferation, activation, and selection of thymocytes by promoting signaling downstream of TCR.• myrAkt mice accumulate memory-phenotype CD4+ T cells, B cells, and develop both tumors and autoimmunity.• Akt overexpression improves survival during sepsis." (PMID 36081513, 2022). "CXCR5+CD8 T cells have slowly come into focus with their unique ability to provide B cell help within germinal centers similar to CD4 Tfh and also maintain a cytolytic capacity in infection, autoimmunity and tumor microenvironments resembling CD8 T effector cells." (PMID 36314014, 2022). "CD4+ T cell responses play important roles in infection, autoimmunity, and cancer." (PMID 35781135, 2022). "Indeed, GM-CSF was reported to mediate autoimmunity by enhancing IL-6–dependent survival of antigen specific CD4+ T cells and promoting generation and maintenance of Th17 cells in vivo." (PMID 36059463, 2022). "We now know these inhibitors of autoimmunity are naïve CD4+CD25+FoxP3+Treg." (PMID 35529847, 2022). "For investigating pericytes in the context of antigen-specific interaction with CD4+ T cells and their subsequent effects in the context of CNS autoimmunity, Pdgfrb-CreERT2 mice were crossbred with Rosa26mTmG reporter animals (hereafter named Pdgfrb-CreERT2-GFP)." (PMID 36361868, 2022). "In this pilot study, we asked whether the ratio and the diversity of the TCR repertoires of circulating memory (CD45RO) and naïve (CD45RA) CD4 T cells could serve as a predictive factor for the development of autoimmunity." (PMID 36458004, 2022). "We next explored transcription factors (TFs) in CD4+ T cells that might be involved in promoting autoimmunity." (PMID 34521820, 2021). "Indeed, strong evidence revealed that Th17 cells represent a distinct subset of CD4+ T lymphocytes that play a critical role in chronic inflammation and autoimmunity in mice." (PMID 33462300, 2021). "In our study, CD4+ memory T cells in the lower FRGScore group were more active, and CD4+ helper T cells provide an opportunity to enhance T cell response to tumor-associated antigens without deleterious autoimmunity." (PMID 34868391, 2021). "Cytotoxic CD4+ T cells are found in other disease settings including infection and autoimmunity." (PMID 34910940, 2021). "Paradoxically, the stimulation of 4-1BB with agonist antibodies also inhibits inflammation in many murine models of autoimmunity, which may be due to augmentation of regulatory CD8 T cell activity and/or driving the death of pathogenic CD4 T cells." (PMID 34685651, 2021). "In addition, the downregulation of IL2 represents a strong evidence of the inhibition of T cells-mediated autoimmunity because IL2 are produced only by CD4+ and CD8+ T cells." (PMID 34650558, 2021). "In this review, we highlight adaptive immune mechanisms in atherosclerosis with a focus on CD4+ T cells, introduce novel technologies to detect ApoB-specific CD4+ T cells at the single cell level, and discuss the potential impact of ApoB-driven autoimmunity in atherosclerosis." (PMID 33669769, 2021). "Furthermore, IL-2 is essential in immunoregulation, as it regulates autoimmunity via the production of CD4+CD25+ T regulatory (Treg) cells." (PMID 34073791, 2021). "We propose that the quiescence induced by the low levels of antigen presentation might be a mechanism necessary to regulate long-term survival of CD4 memory T cells and to prevent cross-reactivity to autoantigens, hence autoimmunity." (PMID 34177919, 2021). "CD4+ CD25+ T cells play an important role in preventing autoimmunity." (PMID 34830017, 2021).
Autoimmunity (continued). "Furthermore, our findings raise the possibility that coinciding epitopes recognized by both CD4+ T cells and B cells have the potential to amplify autoimmunity and promote the development and progression of RA." (PMID 33507879, 2021). "Nonetheless, a possible argumentation for the causative link between ATG and AT1R-Ab may result from the complete and prolonged depletion of the regulatory T cell subset (CD4+ CD25+), thus leading to the loss of self-tolerance and autoimmunity." (PMID 34830672, 2021). "In addition, regarding APECED pathogenesis, a key contributor is a defect in the CD4+CD25+ regulatory T cells that normally intervene to prevent autoimmunity and peripheral tolerance." (PMID 34948375, 2021). "We provide data on 41 in vitro expanded polyclonal CD4+CD127lo/‐CD25+ PolyTreg products manufactured for 7 clinical trials in patients with autoimmune conditions, patients who have undergone kidney transplantation, or patients receiving de novo pancreatic islet transplant." (PMID 34867967, 2021). "Indeed, activation of both CD4+ and CD8+ lymphocytes in acute infection has been associated with the development of a wide array of autoimmune conditions." (PMID 34025675, 2021). "Patients who later developed autoimmunity presented some subtle differences at baseline on T cells, including lower percentages of CD4+ T cells, particularly of terminally differentiated and effector memory cells, and also lower values of CD8+ T cells producing TNF-alpha." (PMID 34691084, 2021). "The identification of CD4+ CTLs in oligo JIA suggests that this population of CD4+ T cells may be important in Th1-mediated autoimmunity, particularly in inflamed peripheral tissues." (PMID 34403374, 2021). "Treg depletion in DBA/1-DEREG mice during immunization aggravated glomerular injury and induced autoantibody production and expansion of autoantigen-specific renal effector CD4+ T cells indicating a protective effect of Tregs during development of autoimmunity." (PMID 33496881, 2021). "Of the activated CD4+ cells, the exception is T CD4+ regulatory lymphocytes (Tregs, regulatory T cells), which inhibit the immune response and are one of the key mechanisms to prevent autoimmunity, including response to food allergens." (PMID 33503831, 2021). "In autoimmunity, CD4+T cell is one of the most important players." (PMID 34140947, 2021). "These cells, originally described to suppress autoimmunity, are named regulatory T cells (Tregs) and represent a subset of CD4+ T helper (Th) cells expressing the forkhead box P3 (Foxp3) transcription factor as well as high levels of the interleukin (IL)-2 high-affinity receptor IL-2Rα or CD25." (PMID 33496881, 2021). "CD4+ T-cell cytokine profile also has a very specific role in autoimmunity in pregnancy." (PMID 34903274, 2021). "Regulatory T cells are a unique subset of CD4+ T cells with immunosuppressive properties; these are essential for maintaining immune homeostasis, self-tolerance, limiting excessive inflammation, and preventing autoimmunity." (PMID 34717747, 2021). "Whether and how the upregulated EGR2 contributes to CD4+ T cell-mediated inflammation of autoimmunity in lupus needs to be further investigated, particularly in vivo in lupus mice with EGR2 deficiency." (PMID 32646370, 2020). "Moreover, other than its suppressive role on T cell-mediated inflammation, EGR2 has also been shown to control autoimmunity by regulating the function of FoxP3 independent CD4+CD25−LAG3+ Treg cells." (PMID 32646370, 2020). "CD4+ regulatory T cells (Tregs) are key mediators of immunological tolerance and promising effector cells for immuno-suppressive adoptive cellular therapy to fight autoimmunity and chronic inflammation." (PMID 33488615, 2020). "Tregs are a special subset of CD4+ T cells that prevent autoimmunity and inflammation." (PMID 33117376, 2020). "Suppressed Fas ligand expression may prevent apoptosis of CD4+ T cells, which may contribute to the development of autoimmunity." (PMID 32973676, 2020).
Autoimmunity (continued). "Importantly, impaired expression of Helios resulted in an unstable CD4+ Treg phenotype, defective CD4+ Treg activity and autoimmunity in mice." (PMID 32528735, 2020). "In addition to providing rapid effector cytokine production, these bystander-activated CD4+ T cells significantly contribute to disease pathology, including that of infection, autoimmunity, and cancer, via their innate-like capacity." (PMID 32859954, 2020). "Use of 2D-micropipette to measure antigen-reactive CD4+ T cells has thus begun to alter our understanding of disease progression during infection and autoimmunity by demonstrating that there is a much higher frequency of antigen specific CD4+ T cells than previously appreciated." (PMID 33120989, 2020). "We propose that loss of IL-10 signaling in CD4+ T cells promotes non-neuroprotective autoimmunity after FNA." (PMID 32303238, 2020). "One mixed result from a phase I clinical trial (NCT02428309) using polyclonal Tregs in SLE found that the administered Tregs were able to traffic to the site of autoimmunity, in this case the skin, yet there was an increase in pro-inflammatory IL-17 from CD4+ and CD8+ cells." (PMID 32977677, 2020). "Tregs are a subset of CD4+ T-cells that play a non-redundant role in the prevention of autoimmunity and is functionally dependent on the X chromosome-linked transcription factor FoxP3." (PMID 33375291, 2020). "Furthermore, the key role of HLA-A-restricted CD8+ T cell responses is initiating autoimmunity and interactions with HLA class II-restricted CD4+ T cell responses." (PMID 33160385, 2020). "During the primary immune response, portions of effector CD4 T cells will be eliminated via apoptosis to avoid autoimmunity, while portions of activated CD4 T cells will become memory CD4 T cells that are more efficient in activation after encountering identical antigens in the future." (PMID 31212664, 2019). "Thus, EPA/DHA-initiated global changes in CD4+ T-cells are likely the primary cellular mechanisms stalling the development of autoimmunity in T1D." (PMID 31611873, 2019). "Observations from animal models have pointed to a critical role of CD4+ T cells and heart-specific autoimmunity in the development of myocarditis and cardiac fibrosis, however, surprisingly little experimental data addressed migration and expansion of autoreactive CD4+ T cells in the EAM model." (PMID 31863205, 2019). "Thus, failure of these CD4+ Foxp3+ T cells to suppress autoimmunity in CD25cKO mice cannot be attributed to their absence in the periphery, but is instead consistent with a lack of suppressive function." (PMID 30833563, 2019). "We have shown that autoreactive CD4+Foxp3GFP− cells from SfTCRmini mice and corresponding cells from TCRmini mice share many identical TCRs that recognize self-peptides as agonists, but the role of these mutual CD4+ clones in autoimmunity and organ damage remain undetermined." (PMID 31653839, 2019). "In other reports, the ablation of Tregs by DT in specific pathogen-free (SPF) or germ-free adult mice led to rapid onset of lethal autoimmunity, demonstrating that many peripheral CD4+Foxp3− cells can be activated by tissue-derived autoantigens unless these cells are stopped by Tregs17,18." (PMID 31653839, 2019). "Furthermore, when identical lymphopenic AbEpTCRα− or AbEp63KTCRα− recipients received an adoptive transfer of naive CD4+ cells from healthy TCRminiAbEp donors, both types of host mice developed lethal autoimmunity." (PMID 31653839, 2019). "The distinction between CVID and CID is extremely important, as a higher incidence of pneumonia, lymphoma, granulomas, autoimmunity, and enteropathy, in addition to lower B-cell and naive CD4 T-cell numbers, accounts for the lower 5-year survival rate in CID patients." (PMID 31803177, 2019). "CD4+CD49b+LAG3+ type 1 regulatory (Tr1) cells are important for controlling autoimmunity and could be involved." (PMID 30863412, 2019).